TLR2 (toll like receptor 2)
Diseases named in the same sentence as TLR2 in open-access papers (continued):
Sharing a sentence is not in itself a finding about the gene and the disease.
periapical granuloma (2 papers, 2018 to 2021). Chronic nonsuppurative inflammation of periapical tissue resulting from irritation following pulp disease or endodontic treatment. "Since the size of a macrophage is typically 20 μm, the detection of the TLR2 in the cytoplasm is best explained by the role they play in periapical granuloma." (PMID 30631444, 2018). "TLR2+ dendritic cells play a minor role in periapical granuloma with regards to antigen recognition." (PMID 30631444, 2018). "This explains the constant expression of TLR2 throughout all cases of refractory periapical granuloma." (PMID 30631444, 2018). "CD38+ cells expressing TLR2+ (CD38+/TLR2+) were identified in all eight periapical granuloma samples and were abundant throughout the lesion." (PMID 30631444, 2018). "The results showed a positive reaction to TLR2 by odontogenic epithelial cells within the refractory periapical granuloma cases." (PMID 30631444, 2018). "In all samples of periapical granulomas, the majority of inflammatory cells and odontogenic epithelium expressed TLR2." (PMID 30631444, 2018). "The consistent expression of TLR2 in the refractory periapical granuloma supports the observation that Gram-positive bacteria play a dominant role in the root canal infection of these lesions." (PMID 30631444, 2018). "The consistent expression of TLR2 within refractory periapical granuloma reported in the current study is in agreement with a number of other studies in the literature." (PMID 30631444, 2018). "The most common TLR2+ cells in refractory periapical granuloma resembled the morphology of lymphocytes and macrophages." (PMID 30631444, 2018). "Refractory periapical granuloma consistently expressed TLR2 through lymphocytes and plasma cells (CD38+), macrophages and monocytes (CD68+) and mature dendritic cells (CD83+)." (PMID 30631444, 2018). "The aim of the study is identification of Toll-like receptor (TLR2) through immunohistochemical and immunofluroscence expression in inflammatory cells within refractory periapical granuloma cases." (PMID 30631444, 2018). "The co-expression of CD68 and TLR2 on cells was identified in five periapical granuloma samples." (PMID 30631444, 2018). "The identification of these lymphocytes and their expression of TLR2 may provide an insight into the effect these cells have on the pathogenesis of refractory periapical granuloma." (PMID 30631444, 2018). "The co-expression of CD83 and TLR2 were identified in six periapical granuloma samples." (PMID 30631444, 2018). "This may suggest the main role of macrophages in the refractory periapical granuloma is to recognize microbes through TLR2 and to perform phagocytosis." (PMID 30631444, 2018). "The results are consistent with dendritic cell expression of TLR2 in periapical granuloma." (PMID 30631444, 2018). "Toll-like receptor 2 expressed on B cells may play two roles within the periapical granuloma." (PMID 30631444, 2018). "The protocol for immunohistochemical procedures of TLR2, CD38, CD68 and CD83 have been standardized and the expression of each cell marker (TLR2, CD38, CD68 and CD83) within refractory periapical granuloma was identified." (PMID 30631444, 2018). "This could explain the fact that TLR2 was not expressed in some of the immune cells within refractory periapical granuloma, as it might have been combined with other members of the TLR family within lesions." (PMID 30631444, 2018).
Peritoneal Fibrosis (2 papers, 2018 to 2024). Disorder characterized by a wide range of structural changes in PERITONEUM, resulting from fibrogenic or inflammatory processes. "Here, we review the findings and discuss the potential of reducing peritoneal TLR activity by using a TLR inhibitor, soluble TLR2, as a therapeutic strategy to prevent PD-associated peritoneal fibrosis." (PMID 30538643, 2018). "The therapeutic potential of inhibiting infection- or PDS-induced TLR activation to prevent peritoneal fibrosis development was evaluated by testing the ability of soluble Toll-like receptor 2 (sTLR2), a TLR inhibitor, to regulate peritoneal inflammation." (PMID 30538643, 2018). "Here, we review the findings and discuss the potential of reducing peritoneal TLR activity by using the soluble form of TLR2, a TLR modulator, as a therapeutic strategy to prevent PD-associated peritoneal fibrosis." (PMID 30538643, 2018). "Together, these findings indicated a major role for TLR2 and to a lesser extent for TLR4 in bacteria-induced peritoneal fibrosis associated with PD, and pointed at controlling infection-induced TLR-mediated activation as a potential therapeutic against peritoneal fibrosis." (PMID 30538643, 2018). "Additionally, the use of antibody blockade targeting TLR2, TLR4, or C5aR showed considerable inhibitory effects on the bacteria-induced release of pro-fibrotic and pro-inflammatory mediators by peritoneal leukocytes in cases of infection-related peritoneal fibrosis." (PMID 39749340, 2024).
plague (2 papers, 2014 to 2017). Plague is a severe bacterial infection caused by the gram-negative bacterium Yersinia pestis. "We earlier showed that deletion of the lpp gene, which encodes Braun lipoprotein (Lpp) and activates Toll-like receptor-2, reduced virulence of Y. pestis CO92 in murine models of bubonic and pneumonic plague." (PMID 29090192, 2017). "It had been previously suggested that weak or inefficient activation of Tlr2 by LcrV makes it unlikely that Tlr2 is involved in pathogenesis by plague." (PMID 24995344, 2014). "Nevertheless, our results suggest that overall, the antibody response to the plague F1-V vaccine did not depend on the presence of Tlr2 or Tlr4." (PMID 24995344, 2014).
polyarthritis (2 papers, 2013 to 2020). "In addition, TLR2−/− mice exhibited a tendency towards higher incidence of polyarthritis compared to the WT mice on day 7 post-infection when they were infected with the Newman parental strain (75% vs 41.7%; P = 0.05)." (PMID 32404866, 2020). "Newman strain induced more severe and frequent clinical septic polyarthritis compared to its Δlgt mutant in TLR2 deficient mice, but not in wild-type controls." (PMID 32404866, 2020). "Secondly, TLR2 deficient mice, lacking staphylococcal Lpp ligand recognition, are more sensitive to S. aureus infection, which lead to more severe and frequent clinical septic polyarthritis." (PMID 32404866, 2020).
polyp (2 papers, 2012 to 2020). A usually exophytic mass attached to the underlying tissue by a broad base or a thin stalk. "The significant relationship between the polyp size and the RQ of TLR2, 3, 4, and, 5 was demonstrated." (PMID 33255933, 2020). "Based on current findings, TLR2 and TLR4 may be upregulated in the process of polyp formation and progression." (PMID 33255933, 2020).
prediabetes (2 papers, 2024). "The contribution of TLRs, specifically TLR2 and TLR4, to the development of prediabetes and diabetic sensory neuropathy has been elucidated by mitigating the inflammatory response in both human subjects and various mouse models." (PMID 38390212, 2024).
Pruritus (2 papers, 2022 to 2023). Pruritus is an itch or a sensation that makes a person want to scratch. "It appeared that TLR2 can upregulate peripheral IL-13Rα2 expression, which led to exaggeration of IL-13-mediated pruritus suggesting that peripheral TLR2-IL-13Rα2 signaling can cause itching sensation and enable neurogenic inflammation." (PMID 37834183, 2023). "Recently, it has been reported that pruritus can be alleviated through the TLR2/4-MyD88-NF-κB pathway using electrical stimulation in a morphine-induced pruritus mouse model." (PMID 35269651, 2022).
pyometra (2 papers, 2018 to 2025). "Notably, the upregulation of COX-2 and PGE synthase (PGES) in pyometra cases, and during the DE and AE stages coincides with TLR-2/4 upregulation, and LPS stimulation synchronously increases COX-2 and mPGES-1 expression, enhancing PGE2 synthesis." (PMID 41150074, 2025).
Q fever (2 papers, 2019 to 2025). A bacterial infection caused by Coxiella burnetii. "Our findings are consistent with previous studies using TLR2- and MyD88-deficient mice and with the association of a polymorphism in human Myd88 with the development of chronic Q fever." (PMID 30800124, 2019). "TLR2 (Arg753Gln) and TLR4 (Asp299Gly, Thr399Ile) polymorphisms, along with HLA-DRB1 alleles, were analyzed for 38 patients with acute Q fever, 38 matched controls, and 121 blood donors." (PMID 40333225, 2025). "To explore this hypothesis, we have decided to investigate the role of TLR2 and TLR4 polymorphisms, as well as the potential influence of HLA alleles, in the development of acute Q fever." (PMID 40333225, 2025). "Specifically, the aim was to identify whether certain TLR2 or TLR4 polymorphisms, or specific HLA-DRB1 alleles, act as risk or protective factors for the development of acute Q fever." (PMID 40333225, 2025).
retinal diseases (2 papers, 2016 to 2022). "Excessive ROS can damage lipids through a mechanism known and conceivably induce activation of TLR2 in AMD and in other retinal diseases where ROS play a role in pathology TLR2 inhibition provides striking protection to the retina in response to oxidative stress." (PMID 35459112, 2022). "TLR2 and TLR4 are expressed widely in various retina cells including Müller cells, retina pigment cells, microglia and astrocytes, made them possible critical mediators in the retinal diseases." (PMID 27297042, 2016).
rheumatic fever (2 papers, 2011 to 2014). A post-bacterial multisystem inflammatory disease occurring as a post-infectious, nonsuppurative sequela of untreated streptococcus pyogenes (Group A streptococcus [GAS]) pharyngitis, and mainly occurs in individuals aged 5 to 15 years. "Hence, the inflammation indicated by the up-regulation of TLR2 in the atria is more likely due to AF, but not rheumatic fever." (PMID 23554687, 2011).
sarcoma (2 papers, 2021 to 2023). A usually aggressive malignant neoplasm of the soft tissue or bone. "In the course of testing TLR2 agonist, the researchers managed to obtain macrophages with a pronounced antitumor potential and achieved a significant increase in the M1/M2 ratio in sarcoma mice in sarcoma mice." (PMID 38136307, 2023).
SARS-CoV Infections (2 papers, 2020 to 2023). "The results obtained from their study indicate that the expression of TLR4/TLR2 is upregulated at 24 h after SARS-CoV infection, suggesting its importance in the generation of immune responses." (PMID 32616763, 2020).
Senile plaques (2 papers, 2011 to 2024). Senile plaques are extracellular deposits of amyloid in the gray matter of the brain. "Microglia associated with senile plaques exhibit elevated levels of TLR2/4/5/7/9." (PMID 21733175, 2011). "Additionally, other studies have demonstrated the increased expression of TLR2, TLR4, TLR5, TLR7, TLR9, and the co-receptor CD14 in microglial cells surrounding senile plaques in the brain tissues of patients with AD and AD mouse models." (PMID 38360834, 2024).
septic peritonitis (2 papers, 2015). Septic peritonitis is an inflammatory condition of the peritoneum that occurs secondary to microbial contamination. "We demonstrate a clear protective effect of the treatment with mAbs against TLR2 or TLR4 in a model of severe polymicrobial septic peritonitis induced by CLP." (PMID 26147469, 2015).
skin abscess (2 papers, 2019 to 2021). "However, the skin abscesses in C57BL/6 TLR2−/− mice caused by OXA-treated N315 were negligibly different from those caused by OXA-treated N315Δlpl, PBS-treated N315, and N315Δlpl." (PMID 31186320, 2019). "S. aureus-induced IL-1β production by neutrophils is TLR2 dependent and known to be crucial for skin abscess formation." (PMID 33785850, 2021).
skin cancer (2 papers, 2021 to 2025). "Inhibits UV-induced skin tumor formation via TLR2 signaling." (PMID 40801650, 2025).
sporotrichosis (2 papers, 2017 to 2024). The commonest and least serious of the deep mycoses, characterized by nodular lesions of the cutaneous and subcutaneous tissues. "TLR-2 and TLR-4 have been reported to be involved in the sporotrichosis-induced immune response." (PMID 38172590, 2024).
staphylococcal pneumonia (2 papers, 2014 to 2017). Pneumonia caused by infections with bacteria of the genus staphylococcus, usually with staphylococcus aureus. "TLR2 recognizes multiple surface components of S. aureus and plays a prominent role in the expression of innate immune responses to acute staphylococcal pneumonia." (PMID 29142002, 2017). "In particular, selective administration of anti-TLR2 or specific TLR regulators early in the florid proinflammatory phase of staphylococcal pneumonia seems theoretically attractive in a condition with continued high mortality despite modern antibiotics and supportive care." (PMID 25478190, 2014).
staphylococcus aureus pneumonia (2 papers, 2016 to 2018). An pneumonia caused by infection with Staphylococcus aureus. "Indeed, MV increased the expression of TLR-2 both in the lungs and systemically after Staphylococcus aureus pneumonia was reported in an animal study." (PMID 30127264, 2018).
Stillbirth (2 papers, 2021 to 2022). Death of the fetus in utero after at least 22 weeks of gestation. "T. gondii infection on gestational day 12.5 (Gd12.5) induced more abnormal pregnancy, including premature birth and stillbirth, in wild-type mice than in TLR2−/− mice." (PMID 34675905, 2021).
streptococcal pneumonia (2 papers, 2013 to 2024). A febrile disease caused by streptococcus pneumoniae. "Both vitro and vivo studies showed that pathogen like streptococcus pneumonia and mycoplasma induce their pathogenic invasion through TLR2 activation, which is dependent on NF-κB pathway." (PMID 27234389, 2013). "In a recent study, a mouse model of OM was created using Tlr2tm1Kir (TLR2−/−) mice, lacking the Tlr2 (Toll-like receptor 2) gene, inoculated in the middle ear (ME) with streptococcal pneumonia peptidoglycan polysaccharide (PGPS)." (PMID 38391409, 2024).
T cell lymphoma (2 papers, 2018 to 2022). "The expression level of TLR2 was similar in LNs from patients with T cell lymphoma and AOSD; however, TLR1, TLR4, TLR7, and TLR9 expression levels were higher in the LNs of patients with AOSD than in T cell lymphoma." (PMID 35715478, 2022). "Jurkat cells (a human CD4+ T cell lymphoma line) have been shown to express most TLRs, and 2G5 cell line in particular has been previously checked for surface expression of TLR2 and TLR4." (PMID 30500820, 2018).
tauopathies (2 papers, 2023 to 2024). "Evidence for TLR2-dependent inflammation in tauopathy was reinforced, as nasal administration of wtTIDM caused downregulation of microgliosis, astrogliosis, and inflammation in the brain." (PMID 37552543, 2023). "TLR2 inhibition in mice with tauopathy results in improved learning and spatial memory retention, and thus, TLR2 is a potential therapeutic target for AD." (PMID 38891900, 2024). "Fourth, wtTIDM-mediated suppression of inflammation was recapitulated in PS19 mouse brain, further emphasizing the involvement of TLR2 in generating glial inflammation in tauopathy brain." (PMID 37552543, 2023). "This study reveals the TLR2/MyD88/NF-κB pathway as the potential link between the signature prerequisite events of progressive neurodegeneration in tauopathy brains: tau aggregation and glial inflammation." (PMID 37552543, 2023). "Therefore, blocking TLR2/MyD88/NF-κB–mediated inflammation with the synthetic peptide wtTIDM holds potential therapeutic value against AD, PSP, FTD, CBD, and other tauopathies." (PMID 37552543, 2023).
Thrombocytosis (2 papers, 2020 to 2024). Increased numbers of platelets in the peripheral blood. "However, we observed through other analyses the high expression of TLR2 in monocytes in high thrombocytosis which appears to be a selective biomarker to high death risk." (PMID 32411797, 2020).
thyroid cancer (2 papers, 2022 to 2025). "Compared to TIMP1 and LOX, the relation between TLR2 and thyroid carcinoma was unclear, especially in PTC." (PMID 36120433, 2022).
Trichinella spiralis infection (2 papers, 2018 to 2026). "Collectively, these findings indicate that Ts-HSP70 modulates macrophage immune functions and may contribute to host defense through TLR2-associated signaling, providing insights into its potential application in vaccine development against trichinellosis." (PMID 42222277, 2026).
triple-negative breast carcinoma (2 papers, 2022 to 2023). An invasive breast carcinoma which is negative for expression of estrogen receptor (ER), progesterone receptor (PR), and human epidermal growth factor receptor 2 (HER2). "This is particularly evident for TLR2, the most expressed TLR in triple negative breast cancer." (PMID 38203626, 2023). "Using two triple-negative breast cancer (TNBC) cell lines MDA-MB-468 and MDA-MB-231, we show that FnEDA and FnIII-1c induce the pro-tumorigenic cytokine, IL-8, by serving as agonists for TLR5 and TLR2, the canonical receptors for bacterial flagellin and lipoprotein, respectively." (PMID 35805158, 2022).
type 2 diabetic nephropathy (2 papers, 2020 to 2023). "The said monoterpene reduced AGEs-induced TLR2/4 activation and inflammatory responses, indicating that it prevents macrophage activation by inhibiting TLR2/4 signaling expression in type 2 diabetic nephropathy." (PMID 38029230, 2023). "On the other hand, PAE reduced macrophage activation by inhibiting TLR2/4 signaling expression in type 2 diabetic nephropathy." (PMID 32153410, 2020).
ulcer (2 papers, 2013 to 2025). "TLR4 and RAGE deficiency enhanced ulcer healing and reduced the level of TNFα, whereas ulcer healing in TLR2 knockout (KO) mice was similar to that in wild-type mice." (PMID 24244627, 2013). "In the ulcer group, MyD88 levels were elevated, signifying an exacerbated inflammatory condition, while the notable rise in TLR-2 levels further emphasizes the intensified inflammatory response." (PMID 40563542, 2025). "Our findings indicated significant elevations in TLR-2/MyD88 levels in the ulcer group." (PMID 40563542, 2025). "A significant up-regulation of TLR2 mRNA was observed following the induction of an ulcer." (PMID 24244627, 2013). "A direct comparison between the ulcer + OMP and ulcer + OMP-NS groups revealed that the OMP-NS formulation significantly decreased levels of HMGB1, NLRP3, NF-κB, TLR-2, MyD88, IL-1β, IL-6, and TNF-α." (PMID 40563542, 2025). "We also investigated which receptor among TLR2, TLR4, or RAGE mediates HMGB1’s effects on ulcer healing." (PMID 24244627, 2013).
viral myocarditis (2 papers, 2021). Myocarditis that is caused by an infection with a viral agent. "TLR2 has been shown to modulate T helper (Th) cell subpopulations in viral myocarditis, while in mice with induced ischemia/reperfusion (I/R) injury, TLR2 facilitates the recruitment of inflammatory lymphocytes to the damaged heart." (PMID 33881711, 2021).
ZIKV infection (2 papers, 2019 to 2026). "Our data show that ZIKV infection induces the expression of TLR2, TLR3, and adaptor molecule MYD88." (PMID 30781519, 2019). "ZIKV infection, for example, reduces the interaction between F-actin and ZO-1, enhancing BTB permeability, whereas mumps virus infection impairs BTB integrity through TLR2-mediated TNF-α production in SCs." (PMID 41596343, 2026).
Abdominal obesity (1 paper, 2019). Excessive fat around the stomach and abdomen. "As the two groups were matched on abdominal fat, it looks that gene expression levels of TLR2, MyD88 and NFĸB are highly related to abdominal obesity than to healthy or unhealthy metabolic state." (PMID 31272370, 2019). "Serum concentration of IL-1β, FFAs, and mRNA expression levels of TLR2, MyD88, and NFĸB may be resulted from abdominal obesity and not be related to the presence or absence of metabolic health." (PMID 31272370, 2019).